ADA (adenosine deaminase)
Diseases named in the same sentence as ADA in open-access papers (continued):
Sharing a sentence is not in itself a finding about the gene and the disease.
Immunodeficiency (96 papers, 2003 to 2025). Failure of the immune system to protect the body adequately from infection, due to the absence or insufficiency of some component process or substance. "For instance, the case of adenosine deaminase deficiency-severe combined immunodeficiency where two children were treated with a recombinant retroviral vector to deliver a normal copy of the adenosine deaminase (ADA) gene into their T-cells." (PMID 40003934, 2025). "The low frequency of such vector-related adverse events reported in γ−RV ADA-SCID GT as compared to the other immune deficiencies indicates that some disease-specific factors alleviate such risk." (PMID 38688902, 2024). "Adenosine deaminase (ADA) deficiency is an ultrarare inherited purine metabolism disorder characterized by severe combined immunodeficiency." (PMID 37506145, 2023). "It is a modified form of bovine adenosine deaminase used to treat severe combined immunodeficiency caused by adenosine deaminase deficiency." (PMID 38033727, 2023). "ADA regulates immune responses, therefore, ADA is reported to be related to immune deficiencies such as acquired immunodeficiency syndrome (AIDS) and leukemia." (PMID 37371990, 2023). "Some immunodeficiency diseases, such as adenosine deaminase (ADA) deficiency, DiGeorge syndrome, and STAT5b deficiency manifested as the abnormal development of cartilage." (PMID 36684670, 2023). "In 1990, the first approved PEG–protein conjugate (PEG–adenosine deaminase, Adagen®) appeared in the market to treat severe combined immunodeficiency caused by an inherited deficiency of the adenosine deaminase enzyme." (PMID 36077451, 2022). "Purine nucleoside phosphorylase deficiency and adenosine deaminase deficiency exhibit aberrant accumulation of dGTP and dATP, respectively and lead to severe immunodeficiencies with insufficient T- and B-cell proliferation." (PMID 35927450, 2022). "ADA deficiency causes early-onset severe combined immunodeficiency, increasing the susceptibility to suffer from infections." (PMID 36009573, 2022). "Previous studies also found that mutations in ADAR (Adenosine deaminase acting on RNA) can cause human immune diseases." (PMID 35711945, 2022). "Our data show that quantitative analysis of ADAs is a sensitive and straightforward way to screen a large population to reveal individuals with ADA deficiencies, immune disorders, and cancer." (PMID 35967411, 2022). "Chemically, Adagen is a PEGylated adenosine deaminase (PEG-ADA, pegademase) nanoparticle approved for the treatment of severe immunodeficiency disease caused by ADA deficiency." (PMID 35456704, 2022). "Adenosine deaminase (ADA) deficiency is an inborn error of metabolism affecting multiple systems and causing severe combined immunodeficiency." (PMID 33738330, 2021). "Adenosine deaminase (or adenosine aminohydrolase) ADA is located at 20q13.12 and is associated with severe immunodeficiency." (PMID 34834471, 2021). "Inherited defects that abrogate the function of the adenosine deaminase (ADA) enzyme and consequently lead to the accumulation of toxic purine metabolites cause profound lymphopenia and severe combined immune deficiency." (PMID 34777360, 2021). "The clinical outcome and test results indicated adenosine deaminase (ADA)-deficient severe combined immune deficiency (SCID)." (PMID 34502390, 2021). "At present, no study describes abnormalities in the development of genitalia or in the pubertal progression of ADA-SCID patients treated for their underlying immune disorder." (PMID 32307643, 2020). "The accumulation of this toxic compound disrupts lymphocyte development and maintenance, which results in severe combined immunodeficiency, a characteristic of adenosine deaminase deficiency." (PMID 31781678, 2019). "Severe combined immune deficiency adenosine deaminase (ADA SCID) deficiency represents 10-15% of human SCID cases." (PMID 31781678, 2019).
Immunodeficiency (continued). "Another study by Hirschhorn and colleagues identified a previously unrecognized missense mutation (G216R) in a patient in eastern Pennsylvania with severe combined immune deficiency due to adenosine deaminase deficiency (ADA-SCID)." (PMID 31781678, 2019). "Adenosine deaminase (ADA) deficiency is considered as an autosomal recessive genetic disease causing the severe combined immune deficiency (SCID)." (PMID 31608113, 2019). "Early clinical trials for adenosine deaminase–deficient severe combined immune deficiency used peripheral T cells transduced with a gammaretroviral vector, and gene-marked cells were detectable more than 10 years after infusion." (PMID 29705247, 2018). "The role of ADA in the cellular immunity was first identified in patients with severe combined immune-deficiency (SCID)." (PMID 30126383, 2018). "Interest in ADA function increased after the discovery that about 15% of inherited immunodeficiencies are caused by mutations in the ADA gene that lead to a loss of function of this protein." (PMID 29497379, 2018). "In fact, neurological abnormalities are far more prevalent in ADA-SCID than other forms of immunodeficiency, indicating that the underlying metabolic disruption caused by ADA deficiency affects the CNS, both in function and development." (PMID 27579027, 2016). "In doing so, we aim to present ADA deficiency as more than an immunodeficiency – it should be recognized as a systemic metabolic disorder that results in multiple organ pathologies." (PMID 27579027, 2016). "2′deoxyadenosine is currently favored as one of the causal factors in the development of immunodeficiency associated with ADA-SCID." (PMID 27579027, 2016). "In doing so, we aim to present ADA deficiency as more than an immunodeficiency and suggest that it should be recognized as a systemic metabolic disorder that affects multiple organ systems." (PMID 27579027, 2016). "Similar bony phenotypes are seen between ADA-deficient mice and Rag2γc−/− mice (another immunodeficiency)." (PMID 27579027, 2016). "They manifest both combined immunodeficiency as well as metabolic abnormalities and are therefore commonly used to assess the effect of ADA deficiency not only on the lymphoid organs and peripheral blood, but also its systemic organ toxicity." (PMID 22969765, 2012). "Nevertheless, autoimmune manifestations have been reported in larger single-center studies on BMT-treated patients with various kinds of immunodeficiencies, including ADA deficiency." (PMID 22969765, 2012). "In about a fifth of ADA-deficient patients, the immune deficiency is initially less severe, presenting later in childhood." (PMID 19830125, 2009). "This is the first report of adenosine deaminase mutation in an Arab patient with severe combined immunodeficiency due to a novel pathogenic mutation in the adenosine deaminase gene." (PMID 19830125, 2009). "This is the first report of adenosine deaminase mutation in an Arab patient with severe combined immunodeficiency." (PMID 19830125, 2009). "We detected a novel mutation in exon 9 of the adenosine deaminase gene (p.Arg282>Gln), which we believe is the cause of the severe combined immunodeficiency phenotype observed in our patient." (PMID 19830125, 2009). "Evidence for the immune-regulatory roles of nucleosides was provided by the identification of immune dysfunction in patients with hereditary loss-of-function mutations in two genes responsible for the breakdown of purine nucleosides: ADA and purine nucleoside phosphorylase (PNP)." (PMID 40519286, 2025).
Immunodeficiency (continued). "Multiple DFSP tumors have been reported in individuals with autosomal recessive ADA-deficient severe combined immune deficiency, although it is unknown if a single pathogenic variant of ADA or variation in other genes increases risk for this cancer." (PMID 39669616, 2024). "Thus, ADA (adenosine deaminase) is essential for lymphocyte production and its deficiency is a cause of severe combined immunodeficiency." (PMID 39247198, 2024). "In the 1990s, there was an acceleration in gene therapy trials, marked by the first authorized attempt to use retroviral vectors expressing adenosine deaminase (ADA) in a gene therapy trial for treating ADA deficiency, which causes severe combined immunodeficiency." (PMID 37111722, 2023). "Indeed, adenosine (and deoxyadenosine) accumulation such as in ADA deficiency, results in severe combined immunodeficiency associated with neurological deficits." (PMID 34054547, 2021). "Mutations of the ADA gene have been identified in patients with severe combined immunodeficiency." (PMID 31781678, 2019). "The ubiquitous expression of ADA means that deficiency can lead to a complex systemic metabolic disorder with multiple organ involvement with potential to cause significant morbidity unrelated to the immunodeficiency." (PMID 29690908, 2018). "ADA deficiency leads to accumulation of toxic deoxy-ATP within cells and immunodeficiency." (PMID 27222657, 2016). "Based on this connection, ADA deficiency induces accumulation of intermediate metabolites due to abnormal nucleic acid metabolism, thereby exerting cytotoxic effects and disrupting lymphocyte differentiation, leading to onset of severe immunodeficiency." (PMID 26549939, 2015). "Adenosine deaminase-deficiency (ADA-SCID) is a kind of immunodeficiency." (PMID 25126554, 2014). "In the context of defective ADA metabolizing enzyme, where the extracellular levels of adenosine are increased, this regulation may be exaggerated and cause immune dysfunction." (PMID 22969765, 2012). "The cause of his immunodeficiency was suspected to be ADA deficiency." (PMID 19830125, 2009). "With its deficiency being a cause of severe combined immune deficiency, ADA plays a key role in the development and function of lymphoid tissues and by regulating surface expression of ADA, CD26 potentially has an important role in adenosine metabolism and immune regulation." (PMID 14520473, 2003). "However, on the other hand, lower levels of ADA are associated with immune deficiency in humans." (PMID 40573424, 2025). "Taken together, dysregulation in a key pathway of nucleotide pools that are necessary for cellular generation and effective DNA damage repair may play an important role in immune dysfunction, as defects in this pathway have been associated with severe immunodeficiency (e.g., adenosine deaminase)." (PMID 33802822, 2021). "There is heterogeneity in the phenotype of ADA-deficiency, with approximately 15–20% of patients exhibiting a ‘delayed clinical onset’ presenting with less severe, but gradually worsening, combined immune deficiency later in life, usually within the first decade, but occasionally in adulthood." (PMID 29690908, 2018). "However, bone defects are also observed in other immunodeficiencies and, therefore, it is unclear whether the bone abnormalities exhibited in ADA deficiency are a result of the perturbations in purinergic metabolism or secondary to the immunodeficiency." (PMID 27579027, 2016). "Thus, reduced expression of ADA may cause induction of autoimmune disease from immunodeficiency, resulting in attack of specific organs." (PMID 26549939, 2015). "Although autoimmunity is frequently observed in certain immunodeficiencies, there is accumulating evidence that ADA deficiency predisposes to this phenomenon not only through general mechanisms of immune dysregulation but also through specific alterations caused by the accumulating ADA metabolites." (PMID 22969765, 2012).
Immunodeficiency (continued). "The first gene therapy was performed in 1990 using the adenosine deaminase (ADA) gene to treat patients with severe combined immunodeficiency." (PMID 38132472, 2023). "The survival profiles of the immunodeficiencies were significantly different (p = 0.0141) and ranged, at 5 years, from 100% for ADA-SCID to 78.8% (95% CI = 61.2–100%) for X-CGD." (PMID 35288539, 2022). "The therapy consisted of a viral vector that delivered a functional copy of the adenosine deaminase (ADA) gene into the T cells of a severe combined immunodeficiency patient." (PMID 32803721, 2021). "The other main isoform of ADA is ADA1, whose deficiency is responsible for a severely combined immunodeficiency (SCID)." (PMID 34577178, 2021). "Strimvelis®, EMA approved in 2016, is indicated for adenosine deaminase deficiency (ADA‐SCID), an immunodeficiency disorder caused by mutations in the gene coding for adenosine deaminase (ADA)." (PMID 34027097, 2021). "Adenosine deaminase (ADA) (OMIM 608958) is an enzyme involved in several disorders related to immunodeficiency and skeletal malformations." (PMID 31275352, 2019). "In summary, AK2 joins RAG1, ADA as well as ITCH and RMRP genes in the list of known causes of immune deficiency in the Amish population." (PMID 31673062, 2019). "It has been shown that several genes are involved in severe combined immunodeficiency, such as the ADA gene." (PMID 31781678, 2019). "In fact, combined immunodeficiency diseases can be seen in humans related to genetically derived impaired ADA function." (PMID 31067716, 2019). "There is for example an extreme case of adenosine deaminase activity in severe combined immunodeficiency (SCID) where activity of 0.11% is sufficient for normal phenotype." (PMID 25647319, 2015). "Regarding the principal differential diagnosis in our case, significant causes of adult onset immune dysfunction that had to be excluded were idiopathic CD4 lymphocytopenia (ICL) and adenosine deaminase (ADA) deficiency." (PMID 24799913, 2014). "In order to cure this immune disorder, PEGylated adenosine deaminase gene has been transferred to T lymphocytes." (PMID 25126554, 2014). "The clinical value of PEGylation was first shown with PEG-adenosine deaminase (PEG-ADA, Adagen®; Enzon Pharmaceuticals), which has been used since 1990 as replacement therapy for immune deficiency due to inherited ADA deficiency." (PMID 16356199, 2006). "The striking manifestations of immune dysfunction in patients with diminished activity of the adenosine metabolizing enzyme adenosine deaminase (ADA), first described in the 1970s, may have contributed to this discrepancy." (PMID 40519286, 2025). "This resembles the situation in ADA-SCID, in which a genetic defect in the ADA1 gene results in increased levels of adenosine and 2’-deoxyadenosine, an early loss of T-, NK- and B-cells and severe immunodeficiency." (PMID 36761184, 2023). "Clinical studies have shown that the levels of ADAs in biological fluids are altered in pathophysiological conditions, suggesting that ADA activity could be a convenient marker for the diagnosis of immune diseases and cancer." (PMID 35967411, 2022). "ADA is a biomarker for inflammatory and immune disorders in pigs." (PMID 36430174, 2022). "Entities with medium- to large-vessel vasculitis as clinical manifestations have been described recently (e.g., adenosine deaminase-2 deficiency, VEXAS-Syndrome), and vasculitis in established autoinflammatory or immunodeficiency diseases is increasingly being identified." (PMID 35920952, 2022). "It was 30 years ago when the first gene therapy had started transfusing autologous T cells that were retrovirally transduced to produce adenosine deaminase (ADA) to two girls aged 4 and 9 years, respectively, with severe combined immunodeficiency due to ADA shortage (ADA-SCID)." (PMID 33589780, 2021). "The first DEG for the set primary immunodeficiency was adenosine deaminase (ADA, FCR = 5.67)." (PMID 31067716, 2019).
Immunodeficiency (continued). "Indeed, it has been used for all our San Raffaele-Telethon Institute for Gene Therapy (SR-TIGET) trials for ADA-SCID, WAS and MLD, as well as in other gene therapy clinical trials for primary immune deficiencies." (PMID 31150018, 2019). "After detailed investigations to rule out an underlying immunodeficiency, we detected a heterozygous ADA gene mutation." (PMID 30327760, 2018). "In other primary immunodeficiency disorders, such molecular chimerism has been linked to atypical and relatively milder disease courses, including ADA-deficient SCID, X-linked ectodermal dysplasia and immunodeficiency, γc deficiency or Wiskott-Aldrich syndrome." (PMID 25205547, 2014). "Lack of ADA causes immunodeficiency and knockout mice die perinatally due to severe liver cell degeneration." (PMID 24070255, 2013). "Although ADA deficiency is more indicative of immunodeficiency, it was proposed that ADA deficiency might be associated with diseases of many non-immunological organ systems." (PMID 40439810, 2025). "The initial, perhaps overly simplistic, expectation was that liver disease would lead to decreased ADA activity; this directional change in M4 was thus unanticipated but suggests an increase in ADA activity and/or expression, possibly due to inflammation and/or metabolic or immune dysfunction." (PMID 40042304, 2025). "It was further shown to be a powerful systemic immunosuppressor, as ADO production was used as an immune escape strategy by pathogens and tumor cells, and its accumulation caused a severe combined immunodeficiency lacking adenosine deaminase (ADA) for Ado degradation." (PMID 37180168, 2023). "In the early 1990s, the first clinical trial of gene therapy for genetic diseases was started using retroviral-mediated transfer of the adenosine deaminase gene into T cells to cure the severe combined immunodeficiency caused by the lack of adenosine-deaminase." (PMID 36239875, 2022). "Common variable immune deficiency could lead to a reduced ADA level, however this patient’s IgG levels were tested and normal." (PMID 34130662, 2021). "However, until 2000 there were indications of the reliability of these therapies in humans, after arduous attempts to improve the technique for the treatment of severe combined adenosine deaminase immunodeficiency (ADA-SCID) (Espinosa and Hernández-Hernández, 2020)." (PMID 34122373, 2021). "Thus, it is suggested that the increased serum ADA levels may indicate the immune dysfunction and poor glycemic control in T2D." (PMID 34001220, 2021). "Recently, the extent of correction of neurological deficits after PEG-ADA treatment has been studied in an animal model of ADA-SCID, the Ada−/− mouse, which showed many features associated with ADA deficiency in humans, including systemic metabolic alterations and immunodeficiency." (PMID 30441833, 2018). "Therefore, bony abnormalities do exist in ADA deficiency, and these appear, in part, to be a non-immunological manifestation and not entirely secondary to the immunodeficiency." (PMID 27579027, 2016). "ADA’s function is essential in maintaining an immune response as patients with ADA deficiency suffer from SCID, a rare inherited metabolic disorder that causes lymphopenia and immunodeficiency due to the accumulation of toxic substrates and excessive adenosine receptor activation." (PMID 23240012, 2012). "A leader of these investigations was the physician-scientist Eloise Giblett, whose interest in purine metabolism began when she identified a complete lack of blood ADA activity in a patient with severe combined immunodeficiency (SCID)." (PMID 40519286, 2025). "ADA-SCID, being a non-lymphocyte-specific cause of immunodeficiency, is unique among the different genetic causes of SCID." (PMID 34502390, 2021). "Nowadays, early ADA restoration, by either enzyme replacement therapy, allogeneic hematopoietic stem cell transplantation (HSCT), or gene therapy, is available and prevents patients from severe immunodeficiency." (PMID 34502390, 2021).